SPARC (secreted protein acidic and cysteine rich)
Diseases named in the same sentence as SPARC in open-access papers (continued):
Sharing a sentence is not in itself a finding about the gene and the disease.
pancreatic ductal adenocarcinoma (7 papers, 2010 to 2024). An infiltrating adenocarcinoma that arises from the epithelial cells of the pancreas. "These differential effects may also be linked to diverging roles of SPARC in the tumor as compared to the stroma, as stromal expression but not tumor expression has been linked to poor patient outcomes in pancreatic ductal adenocarcinoma." (PMID 33534863, 2021). "Collectively, our data revealed SOX8/EZH2/SPARC signaling induced primary chemo-resistance of albumin-bound paclitaxel in pancreatic ductal adenocarcinoma." (PMID 35173526, 2022). "Recent bioinformatics analysis on a prognostic biomarker in pancreatic ductal adenocarcinoma suggests SPARC as a potential biomarker for this disease." (PMID 36415513, 2022). "For example, SPARC overexpression has been correlated with tumor metastasis in breast invasive ductal carcinoma, glioblastoma, pancreatic ductal adenocarcinoma, clear-cell renal cell carcinoma, melanoma, and prostate carcinoma." (PMID 26926673, 2016). "The aim of this study was to characterise the function of SPARC and its modulation by fibroblast growth factor receptor (FGFR) 1 isoforms in pancreatic ductal adenocarcinoma (PDAC)." (PMID 19920824, 2010). "Some literatures found that high stromal SPARC expression in the primary tumor might be a biomarker for Nab-PTX treatment of inferior PFS and OS in advanced pancreatic ductal adenocarcinoma and better survival in NSCLC." (PMID 29152093, 2017).
sarcoma (7 papers, 2013 to 2025). A usually aggressive malignant neoplasm of the soft tissue or bone. "There was overexpression or loss of other sarcoma relevant proteins such as SPARC, PTEN and MGMT." (PMID 25906748, 2015). "Among them, COL1A1, PDGFRB, and SPARC were confirmed as sarcoma-related genes using the GEPIA database." (PMID 41040657, 2025). "Because secreted protein acidic and rich in cysteine (SPARC) shows high binding affinity to albumin, a study has proved that pediatric sarcoma xenografts expressing SPARC would show enhanced uptake and accumulation of nab- paclitaxel." (PMID 35223497, 2022). "In sarcoma, SPARC has recently been suggested as a potential prognostic factor in a relatively small study." (PMID 27544129, 2016). "The small sample size precludes adequate power to detect differences in SPARC expression between the various subtypes of sarcoma." (PMID 27544129, 2016). "Twenty-seven sarcoma specimens were obtained at varying time points in the patients’ clinical courses and evaluated for SPARC expression." (PMID 27544129, 2016). "In this study, we analyzed SPARC expression in sarcoma patients and found that 70 % of tumors demonstrated some SPARC expression, including 44 % with high SPARC expression." (PMID 27544129, 2016). "Though, SPARC expression has been assessed in sarcoma specimens, only 1 case of angiosarcoma has previously been evaluated and was found to have high expression of SPARC." (PMID 25906748, 2015). "Through this analysis, COL1A1, PDGFRB, and SPARC were identified as sarcoma-related genes." (PMID 41040657, 2025). "Future studies might focus on prospective evaluation of SPARC expression in sarcoma, especially in a cohort of patients treated with albumin-bound agents." (PMID 27544129, 2016). "As nab-paclitaxel or other chemotherapy agents that bind to albumin such as aldoxorubicin are evaluated in sarcoma, the use of SPARC as a predictive biomarker might be considered." (PMID 27544129, 2016). "The sarcoma tissue specimens were assessed for SPARC expression level via IHC." (PMID 24484617, 2014). "The positivity of SPARC indicates that there may be greater delivery of albumin-bound paclitaxel to the malignant sarcoma, since SPARC is a facilitator that allows more chemotherapeutic agents to concentrate in the surrounding tumoral microenvironment." (PMID 23895135, 2013). "High, low, and no SPARC expression was found in 22, 13, and 15 primary sarcomas, respectively and in 5, 4, and 8 recurrent sarcomas, respectively." (PMID 27544129, 2016). "In the primary sarcoma specimens, more patients with high SPARC expression had been pre-treated with GT, while more patients with no or low SPARC expression had been pretreated with AI." (PMID 27544129, 2016). "Compared with other malignancies, there is limited data on SPARC expression in sarcoma, and there is no uniformly accepted determinant of high vs. low expression." (PMID 27544129, 2016). "Various subtypes were included and SPARC expression was not assessed, and given the small sample size and heterogeneity of tumor types, no conclusions as to the efficacy of nab-paclitaxel in sarcoma could be drawn from this study." (PMID 27544129, 2016).
chronic pancreatitis (6 papers, 2010 to 2024). A chronic inflammatory process causing damage and fibrosis of the pancreatic parenchyma. "SPARC has been shown to be an early marker that permits the differential diagnosis between PC and chronic pancreatitis." (PMID 37760400, 2023). "Accumulated evidence shows that the methylation profiles of certain genes in cfDNA are useful markers for distinguishing between chronic pancreatitis and cancer, and in certain cases, such as SPARC, may be an early marker of the disease." (PMID 37760400, 2023). "Further, it was demonstrated that SPARC expression is attenuated during chronic pancreatitis." (PMID 26110898, 2015). "Another group found SPARC and NPTX2 hypermethylation can distinguish PDAC from healthy controls and patients with chronic pancreatitis." (PMID 39409954, 2024).
gastric tumors (6 papers, 2010 to 2023). "Moreover, SPARC expression is dramatically increased in gastric tumors and associated with poor outcome." (PMID 32934754, 2020).
gestational diabetes (6 papers, 2013 to 2022). Carbohydrate intolerance first diagnosed during pregnancy. "A cross-sectional study on women with gestational diabetes mellitus showed higher SPARC and lower adiponectin levels as compared to normal glucose tolerance controls." (PMID 33192583, 2020). "Furthermore, serum levels of SPARC are associated with insulin resistance, dyslipidemia and inflammation in patients with gestational diabetes mellitus (GDM)." (PMID 29760587, 2018). "More importantly, elevated plasma SPARC levels are potentially linked to the pathogenesis of T2DM, and inflammation in gestational diabetes mellitus." (PMID 26110898, 2015). "However, among these peptides, the role of adipocyte-specific fatty-acid-binding protein (AFABP), chemerin, and secreted protein acidic and rich in cysteine (SPARC) in gestational diabetes (GDM) has not been fully investigated." (PMID 34007846, 2021). "We aimed to determine whether concentrations of SPARC were altered in patients with gestational diabetes mellitus (GDM) compared to normal glucose tolerance (NGT) controls and to investigate the relationships between SPARC and metabolic parameters in pregnant women." (PMID 24349098, 2013).
ischemic stroke (6 papers, 2018 to 2025). A stroke disorder caused by obstruction of blood flow to the brain, due to thrombotic (local blood clot formation) or embolic (due to a blood clot or other material traveling from another site) event. "In this study, we show that SPARC is upregulated in a model of ischemic stroke and following OGD and identify a novel role for SPARC in selectively regulating GluA1-containing Phx-433 sensitive AMPARs at hippocampal synapses." (PMID 29449802, 2018). "To explore the potential side effects of these targets, we analyzed whether druggable genes influence ischemic stroke and found that TNFSF12, SLC22A4, and SPARC influence the occurrence of certain ischemic stroke subtypes." (PMID 38977622, 2025). "The post-SAH time course of SPARC and integrin αVβ3 levels have never been determined, while expression of integrin αVβ3 in microvessels after experimental ischemic stroke is significantly increased at 2 h poststroke in adult baboons." (PMID 34804372, 2021). "However, how the SPARC interaction with hevin is affected during ischemic stroke is not known and further experiments are needed to fully understand the neuroprotective role of SPARC." (PMID 39086680, 2023).
keloid (6 papers, 2022 to 2025). An irregularly shaped, elevated mark on the skin caused by deposits of excessive amounts of collagen during wound healing. "The results of the FOXP1-Cut&Tag experiment in keloid fibroblasts revealed that FOXP1 is associated with the SEs of SERPINH1, MMP14, COL5A1, COL16A1, and SPARC, all of which exhibited significant signal enrichment in their SE regions." (PMID 40702440, 2025). "We detected the expression of SPARC in keloid, extra-lesional, and normal skin tissues through employing immunohistochemistry staining, qRT-PCR, and western blot." (PMID 39482755, 2024). "This study aimed to explore the function of secreted protein acidic and cysteine rich (SPARC) on keloids and its behind exact mechanisms." (PMID 39482755, 2024). "The effects and the behind exact mechanisms of SPARC on keloids may be complex and not fully understood." (PMID 39482755, 2024). "However, the precise molecular mechanism of SPARC on keloids is complex and not fully understood at present." (PMID 39482755, 2024). "Therefore, we investigated the effect and potential mechanisms of SPARC on keloids." (PMID 39482755, 2024). "Our findings indicated that SPARC could activate p38γ pathway to stabilize the expression of PFKFB3, and thus promote the glycolysis of KFs and the progression of keloid." (PMID 39482755, 2024). "Collectively, we speculated that SPARC might regulate the p38γ pathway to stabilize the expression of PFKFB3, and thus participated in the glycolysis process of KFs and the progression of keloid." (PMID 39482755, 2024). "After transfected with pcDNA-SPARC, si-SPARC-1#, si-SPARC-2#, and si-p38γ, and treated with glycolytic inhibitor (2-DG) or p38 inhibitor (SB203580), CCK-8, EdU, transwell, and western blot were utilized for assessing the proliferation, migration, and collagen production of keloid fibroblasts (KFs)." (PMID 39482755, 2024). "Thus, we hypothesized that SPARC might regulate the p38γ pathway to stabilize the expression of PFKFB3 protein, thereby participating in the glycolysis of KFs and keloid progression." (PMID 39482755, 2024). "Our findings verified that SPARC could activate p38γ pathway to stabilize the expression of 6-phosphofructo-2-kinase/fructose-2,6-biphosphatase 3 (PFKFB3), and thus participate in the glycolysis of keloid fibroblasts and the progression of keloid." (PMID 39482755, 2024). "In conclusion, our work demonstrated that SPARC could activate the p38γ pathway to stabilize the expression of PFKFB3, and thus promote the glycolysis of KFs and the progression of keloid, implying that SPARC/p38γ/PFKFB3 signaling axis may be a new molecular mechanism in the therapy of keloids." (PMID 39482755, 2024).
leukemia (6 papers, 2008 to 2022). A malignant (clonal) hematologic disorder, involving hematopoietic stem cells and characterized by the presence of primitive or atypical myeloid or lymphoid cells in the bone marrow and the blood. "On the other side, lymphomas and types of leukemia with SPARC overexpression presented increased tumor growth." (PMID 31934533, 2019). "Aberrant hypermethylation of the SPARC promoter has also been observed in cancers of the lung, prostate, endometrium and leukaemia cell lines." (PMID 18458674, 2008).
lung adenocarcinoma (6 papers, 2010 to 2022). A carcinoma that arises from the lung and is characterized by the presence of malignant glandular epithelial cells. "The functional effect of SPARC promoter methylation on its expression was analyzed in two independent TCGA datasets of 877 lung adenocarcinomas (LUADs) and 765 lung squamous cell carcinomas (LUSCs)." (PMID 32580473, 2020). "Three of the nine-examined early EMT hallmark genes, GALNT6, SPARC and HES7, were up-regulated specifically in the early stages of lung adenocarcinoma (LUAD) and confirmed by TCGA patient transcriptome data." (PMID 31296175, 2019). "SPARC expression was also higher in lung squamous cell carcinoma than in lung adenocarcinoma." (PMID 35211625, 2022). "By analyzing LUAD dataset from TCGA, we found three EMT markers (GALNT6, SPARC and HES7) among the nine in vitro identified genes with known function are also up-regulated in specifically in early stage lung adenocarcinoma patients." (PMID 31296175, 2019). "SPARC is an extracellular matrix protein that has been shown to function as an inhibitor of angiogenesis, and in lung adenocarcinomas SPARC methylation has been correlated with a negative prognosis." (PMID 20546602, 2010).
metastatic tumors (6 papers, 2013 to 2021). "Conversely we observed genes associated with aggressive metastatic disease and EMT (VIM, SPARC, ZEB1, SNAI2, CTSB) upregulated in lung populations compared to lymph nodes." (PMID 34579762, 2021). "Two markers of stromal tumor response (PDGFRB, SPARC) showed marked differential expression between primary ovarian and metastatic tumor samples." (PMID 24204986, 2013). "Remarkably, 14 out of 16 primary metastatic tumors, and 1 out of 14 non-metastatic tumors analyzed, also displayed unequivocal staining for SPARC in their epithelial tumoral components." (PMID 25331979, 2014). "Analysis of stroma enriched samples also revealed that SPARC and COLIA1 expression in the stromal compartments of both primary and metastatic tumour were highly significant (p ≤ 0.001) while these targets were only significantly enriched in metastatic tumours in whole biopsy analysis." (PMID 31959771, 2020).
prostate tumor (6 papers, 2008 to 2024). "SPARC was up regulated in endothelial cells with a significant q-value of 8.4 × 10-10 and also significantly up regulated in brain, colon, kidney and prostate tumour tissue." (PMID 18394197, 2008). "Thus, in order to further establish the origin of the observed staining for SPARC in prostate tumor samples, real-time PCR was performed on RNA samples isolated from laser-microdissected epithelial or stromal components of non-metastatic or metastatic primary tumors." (PMID 25331979, 2014).
renal carcinoma (6 papers, 2012 to 2023). A carcinoma arising from the epithelium of the renal parenchyma or the renal pelvis. "DCN was identified as a renal cancer prognostic marker with lower levels of its protein identified in glomeruli cells of normal kidneys whereas higher levels of SPARC was predicted in glomeruli and lower levels in tubuli cells of normal kidneys." (PMID 34557161, 2021). "In renal cancer, SPARC mediates TGF-β-induced metastasis by facilitating cancerous invasion." (PMID 36604669, 2023). "Furthermore, SPARC is a key mediator of TGF-β-induced renal cancer and metastasis." (PMID 35721704, 2022). "Meanwhile, SPARC has also been studied solely in KIRC, which implied that it might be a key mediator of TGF-β-induced renal cancer metastasis." (PMID 38035023, 2023). "Regarding SPARC, recently, it has been demonstrated that it is a key mediator of TGF-β-induced renal cancer metastasis and represents a negative prognostic marker of RCC patient survival." (PMID 34440012, 2021).
rheumatoid arthritis (6 papers, 2007 to 2025). A chronic, systemic autoimmune disorder characterized by inflammation in the synovial membranes and articular surfaces. "SPARC is overexpressed in inflammatory conditions such as rheumatoid arthritis and different types of cancer." (PMID 38994944, 2024). "A growing number of studies have suggested that the downregulation of SPARC is likely to be a major precipitating event in the pathogenesis of rheumatoid arthritis." (PMID 38022508, 2023). "Based on the pathological phenomenon of high-level expression of SPARC in rheumatoid arthritis and tumors, it is more feasible for functional nanomaterials to deliver drugs directly to the lesion." (PMID 37577749, 2023). "SPARC-based nanomedicines have strong potential for rheumatoid arthritis therapy by inhibiting the secretion of pro-inflammatory cytokines." (PMID 38022508, 2023). "This article will introduce the regulatory mechanism and research progress of SPARC in rheumatoid arthritis and tumors in detail." (PMID 37577749, 2023). "SPARC has been observed to increase in both OA and rheumatoid arthritis." (PMID 39777501, 2025). "This article comprehensively summarizes the mechanism of SPARC overexpression in inflammation and tumors as well as the latest research progress of functional nanomaterials in the therapy of rheumatoid arthritis and tumors by manipulating SPARC as a new target." (PMID 37577749, 2023).
systemic sclerosis (6 papers, 2008 to 2025). A chronic disorder, possibly autoimmune, marked by excessive production of collagen which results in hardening and thickening of body tissues. "A current Study has shown that SPARC induced TGF-β signaling promotes pro-fibrotic activation of systemic sclerosis patient dermal fibroblasts." (PMID 39481283, 2024). "SPARC is abundantly expressed in fibrotic disorders such as systemic sclerosis, pulmonary, and renal interstitial fibrosis." (PMID 37569556, 2023). "SPARC, overexpressed in the fibroblasts of skin biopsy specimens obtained from patients with systemic sclerosis, could be the factor involved in the interstitial fibrosis seen in muscles of LGMD2A patients." (PMID 19015733, 2008).
viral infection (6 papers, 2012 to 2024). "Not only is SPARC able to prevent a decrease in cardiac function, but it is also able to rescue myocytes that are already compromised through viral infection." (PMID 30933983, 2019). "Real-time q-RT-PCR, Western Blot and ICC were also performed to investigate the changes of SPARC expression after viral infection." (PMID 23050783, 2012). "The similar data were achieved in S1 and HO8910PM cells following SPARC shRNA virus infections." (PMID 22879971, 2012). "The SPARC/osteonectin, cwcv and kazal-like domains proteoglycan 2 (SPOCK2) is a complex type of secreted proteoglycan involved in forming a protective barrier against viral infection." (PMID 33244319, 2020). "But in this study, intracellular SPARC did not change the expression of integrin β1 and integrin β3 after viral infection." (PMID 22879971, 2012).